TNF (tumor necrosis factor)
Diseases named in the same sentence as TNF in open-access papers (continued):
Sharing a sentence is not in itself a finding about the gene and the disease.
pulmonary TB (109 papers, 2005 to 2025). "In pulmonary TB patients with cavities, elevated TNF levels in bronchoalveolar fluid are associated with necrosis, enhanced collagenase activity, reduced collagen synthesis, and cytotoxic effects on epithelial cells, contributing to lung damage." (PMID 40427602, 2025). "Here we report two adults with recurrent pulmonary tuberculosis who are homozygous for a private loss-of-function TNF variant." (PMID 39198650, 2024). "It has been found that variants of IL1B were associated with latent tuberculosis infection, whereas variants of IL6 and TNFα variants were associated with pulmonary tuberculosis." (PMID 35153741, 2021). "In addition to the use of TNF-α inhibitors, the inherited TNF deficiency has been identified as a genetic aetiology of recurrent pulmonary TB in adults observed within 1 year of the end of treatment." (PMID 39963138, 2025). "It has been proposed that TNF-α gene polymorphisms may be associated with lead-induced inflammatory response, beryllium-induced chronic beryllium disease, and risk of pulmonary tuberculosis in iron miners with exposure to silica dust." (PMID 31652851, 2019). "The aim of our study was to investigate whether IL6–174 G>C SNP and IL17A -197 G>A polymorphism and additional cytokine genes involved in immune response to MTB (IL2, IL4, IL10, IFNG and TNF) are associated with genetic susceptibility to pulmonary TB (PTB)." (PMID 26840977, 2016). "A meta-analysis involving 98,483 patients treated with at least one anti-TNF agent reported 947 cases of active TB, of which 62.2% were pulmonary TB." (PMID 40711067, 2025). "In patients with active pulmonary TB, there are increased levels of autoantibodies to TNF of the IgG class and IgG3 subclass compared to healthy donors." (PMID 40427602, 2025). "In patients with pulmonary TB with increased content of serum TNF, the levels of its soluble type 1 and 2 receptors were also increased." (PMID 40427602, 2025). "In patients with pulmonary TB with an advanced infectious process, the level of anti-TNF autoantibodies of the IgG class and subclasses of IgG1 and IgG3 is higher compared to patients with a limited infectious process." (PMID 40427602, 2025). "Pulmonary TB is driven by persistent inflammation, involving pro-inflammatory cytokines such as tumor necrosis factor-alpha, interleukin-6 and interferon-gamma." (PMID 40978039, 2025). "Changes in the serum levels of the proinflammatory cytokines TNF-α, IL-6, and IL-1β in the two groups of pulmonary tuberculosis patients before and after antituberculosis treatment were detected via ELISA." (PMID 40129950, 2025). "Some studies have found that the levels of IL-6 and TNF-α inflammatory cells increase in pulmonary tuberculosis, which is similar to the conclusion of this study." (PMID 39258673, 2024). "Studies have shown that reactivation of pulmonary TB occurs in latently infected mice upon the neutralization of TNF-α." (PMID 39066368, 2024). "Among the 13,913 adult patients who received TNF-α antagonists, 68 developed TB disease comprising of 59 cases of pulmonary TB and 9 cases of disseminated TB." (PMID 39639969, 2024). "One patient treated with TNF-α and IL-12/23 inhibitors developed pulmonary tuberculosis (EAIR, 1.9 and 0.9 per 1000 PY, respectively)." (PMID 38137722, 2023). "Here, we show that adenoviral vector codifying for TNF has a protective effect during pulmonary TB in a murine model of infection with MDR-Mtb, by up-regulating cells expressing a key protective cytokine like IFN-γ in pneumonic areas." (PMID 38138078, 2023). "Men had higher IL6, IL8, and TNFα levels than women, and female patients’ and healthy controls’ IL8 and TNFα levels were similar, supporting the notion that men are the main contributors to the highly pro-inflammatory profile observed in pulmonary TB patients." (PMID 35454079, 2022). "In extra pulmonary TB, tumor necrosis alpha (TNF-α) possess a more pro-inflammatory cytokine profile compared to pulmonary TB." (PMID 35198736, 2022).
pulmonary TB (continued). "Consistent with our cell culture observations, TNF-α immunostaining was extensive in a biopsy from a patient that developed pulmonary TB whilst treated with pembrolizumab, an anti-PD-1 antibody." (PMID 32091388, 2020). "It is also interesting, that all 9 detected TB cases in our study had pulmonary TB, when it is reported that extrapulmonary forms account for almost 60% of cases and disseminated forms for 26% of patients treated with TNF inhibitors." (PMID 32764422, 2020). "These include, people living with HIV, contacts of pulmonary TB cases, patients initiating anti-tumor necrosis factor therapy, patients receiving dialysis and patients preparing for transplantation." (PMID 32099659, 2020). "Similar to TNFα, it has recently been demonstrated that circulating levels of this cytokine are elevated in human patients with active pulmonary tuberculosis, and that these levels decline significantly over a six month course of therapy." (PMID 30470763, 2018). "Several studies have demonstrated the presence of functional Mtb-specific CD4+ T cell responses in treatment-naïve pulmonary TB patients by assessing the production of IL-2, TNF-α, and IFN-γ in PBMCs stimulated with Mtb antigens." (PMID 29983703, 2018). "These groups include people living with HIV, recently infected persons, adult and child contacts of pulmonary TB cases, and tumor necrosis factor (TNF) and transplantation patients." (PMID 29281987, 2017). "IL-32, a novel pleiotropic cytokine capable of inducing pro-inflammatory cytokines such as TNF-α and IL-1β and elevated in the sera of active pulmonary TB, can be triggered by IL-12." (PMID 27634911, 2016). "In previous studies, TNF-α level has been found to be higher in BALF in patients with pulmonary TB than that in healthy controls." (PMID 22889060, 2012). "Increased levels of TNF-α are commonly detected in culture supernatants of peripheral blood mononucleated cells (PBMCs) from patients with pulmonary tuberculosis stimulated with mycobacterial antigens." (PMID 23251798, 2012). "Serum levels of the Th1 cytokines INFγ and TNFα were significantly elevated in both pulmonary sarcoidosis and pulmonary tuberculosis compared to healthy volunteers." (PMID 22815689, 2012). "Assessment of the TNF-α/IL-2 ratio derived of CD4+ T cells revealed increased TNF-α in patients suffering from extra-pulmonary TB, suggesting a more pro-inflammatory cytokine profile if compared to pulmonary TB." (PMID 22523581, 2012). "Additional studies have shown that thalidomide treatment, in combination with antibiotics, reduces TNF-α production in patients with pulmonary TB and can improve treatment outcome." (PMID 21949656, 2011). "Studies from our group and others have shown that generalized immune suppression by anti-TNF-α antibody treatment in the mouse model of pulmonary TB compromised the ability of the animals to control bacillary growth, and exacerbated the pathology in the lungs." (PMID 21949656, 2011). "LPS stimulated CCL2 and TNFα responses were also raised in pulmonary tuberculosis as compared with extra-pulmonary tuberculosis patients." (PMID 16001981, 2005). "We determined circulating levels of CCL2, CXCL8 and TNFα in sera of pulmonary and extra-pulmonary tuberculosis patients and controls." (PMID 16001981, 2005). "Serum levels of CCL2, CXCL8 and TNFα were measured in patients with pulmonary tuberculosis (N = 12), extra-pulmonary tuberculosis (N = 8) and BCG-vaccinated healthy volunteers (N = 12)." (PMID 16001981, 2005). "In this Eastern-Romanian cohort, pulmonary tuberculosis exhibited a distinct hyper-TNF-α systemic profile that strongly correlated with early in-hospital mortality, while the levels of inflammatory cytokines such as IL-1β were significantly higher than in controls." (PMID 40806949, 2025).
pulmonary TB (continued). "Cytokines such as IL-1, sIL-2R, TNF-α, IL-5, IL-6, and IFN-γ play important roles in pulmonary tuberculosis patients, and their elevated levels may be associated with disease severity and inflammatory status." (PMID 39432654, 2024). "Regardless of these limitations, our results could help understand anti-TNF agents’ effects as a driver of MDR-TB in patients with pulmonary TB." (PMID 37035321, 2023). "Our findings suggest that serum levels of TNF-α increase in patients with pulmonary tuberculosis." (PMID 30588415, 2018). "Moreover, myeloid and T cell TNF act collectively in pulmonary tuberculosis resembling the effect of overall TNF." (PMID 28280495, 2017). "We also examined whether neutralizing the IL-6 receptor affected PPD-induced changes in the frequency of IFN-γ-, IL-2-, TNF-α-, and IL-17A-producing cells in pulmonary TB patients with T2DM." (PMID 27783671, 2016). "Within this scenario, the strong positive correlation of IFN-γ and TNF-α with IL-10 production during the establishment of clinical cure of pulmonary tuberculosis seems to contribute to the control of the microorganism without inducing exacerbated tissue damage." (PMID 23824716, 2013). "The coordinate increase in CCL2 and TNFα responses observed in the pulmonary TB group, may indicate active monocyte recruitment to the lungs which are likely to facilitate granuloma formation and localization of M. tuberculosis infection." (PMID 20041183, 2009). "Treatment with an anti-TNF agent could be a driver of MDR-TB in patients with pulmonary TB." (PMID 37035321, 2023). "Circulating miR-206, for example, correlates with high TNF-α/IFN-γ levels and independently predicts drug resistance in Chinese pulmonary TB cohorts." (PMID 40806949, 2025). "Heterogeneity was assessed for biomarkers that reported sensitivity and specificity in at least four studies for adult pulmonary TB (CRP, HO-1, IFN-γ, IL-6, IP-10, MIG, TNF, and VEGF)." (PMID 39445833, 2024). "For example, IL-32 is linked to the balance of Th1/Th17 cytokines in the peripheral blood of patients with pulmonary tuberculosis and high levels of IFN-γ and TNF-α expression in T cells in lung tissue of IL-32γ-transgenic mice infected with Mtb." (PMID 38803498, 2024). "The expression of significant cytokines in the immune response during pulmonary TB (IFN-γ, IL-4, TNF- α, and TGF-β) was determined." (PMID 37284503, 2023). "CCL2 level was observed to be positively correlated with IL12p70, IFN-γ and TNF-α, thus suggesting the immunological regulatory role of CCL2 against pulmonary tuberculosis." (PMID 33381602, 2020). "Th1 cytokines, such as TNF-α and IFN-γ, have been classically regarded as correlates of protection during advanced pulmonary tuberculosis." (PMID 33679685, 2020). "CCL2/MCP-1, IL12p70, IFN-γ, TNF-α, and TGF-β were measured in serum samples of 120 pulmonary TB patients and 54 healthy controls." (PMID 33381602, 2020). "Although only one case refers to pulmonary TB-IRIS [occurring after interruption of prior anti-TNF-α treatment], these case reports support the possible benefits of TNF-α blockers in the treatment of (complicated) TB." (PMID 30425706, 2018). "miR-144* is overexpressed in T cells from patients with pulmonary tuberculosis and is suggested to suppress IFN-γ and TNF-α production and T cell proliferation." (PMID 24130753, 2013). "The classical cytokines such as IL-2, TNF-α, IL-6 and IFN-γ, have been reported to correlate with disease activity during active pulmonary TB." (PMID 23626814, 2013). "Our results indicate that clinical cure of pulmonary tuberculosis is characterized by recovery in IFN-γ production capacity and by enhancement of TNF-α production." (PMID 23824716, 2013). "In response to LPS stimulation, patients with pulmonary tuberculosis showed increased CCL2 and TNFα responses as compared with the extra-pulmonary group." (PMID 16001981, 2005).
pulmonary TB (continued). "Previous studies have shown that in vivo (circulating) serum levels of IFNγ, IL-10, TNFα, CXCL8 and IL-6 are raised in pulmonary tuberculosis." (PMID 16001981, 2005). "Further,we analyzed the different genera present in pulmonary TB patients with and without injury at T2 and their correlations with the inflammatory factors TNF-α, IL-6, and IL-1β." (PMID 40129950, 2025). "Similarly, an earlier study has shown that treatment with a PDE4i such as roflumilast and rolipram controlled the neutrophil recruitment by reducing TNF-α, IL-6, CXCL1, and CXCL2/3 in a rabbit model of pulmonary TB." (PMID 37854602, 2023). "It was reported that the synthesis of cytokines in pulmonary TB with DM patients showed significant changes compared to pulmonary TB without DM, such as IL-2, IL-6, IL-17, TNF-α and IFN-γ." (PMID 38027218, 2023). "In the case of the progressive pulmonary TB model, we evaluated ctpF transcript levels at 21 and 60 dpi, as in this model 21 dpi (acute or early phase) is the time of maximal protective activity mediated by IFN-γ, IL-12, TNF and NO production." (PMID 35682696, 2022). "To further characterize the effect of vaccination on pulmonary TB pathogenesis, we evaluated the production of TNF-α, IL-17, and IL-10 in lungs of vaccinated/non-vaccinated and infected guinea pigs." (PMID 34127755, 2021). "It was reported that the synthesis of cytokines in pulmonary TB with DM patients shown significant changes compared to pulmonary TB without DM, such as IL-2, IL-6, IL-17, TNF-α and IFN-γ." (PMID 34134685, 2021). "The frequency of IFN-γ- (1.7-fold, p = 0.0002), IL-2- (2.1-fold, p = 0.0001), TNF-α- (1.6-fold, p = 0.0005), and IL-17A- (2-fold, p = 0.0004) producing cells was significantly higher in diabetic than in non-diabetic pulmonary TB patients." (PMID 27783671, 2016). "Pulmonary TB patients displaying the highest concentrations of HO-1 in plasma exhibited significantly elevated plasma levels of interleukin (IL)-10, interferon (IFN)-γ and IL-17 and diminished levels of tumor necrosis factor (TNF)-α." (PMID 23671613, 2013). "Two patients had a history of appropriately treated pulmonary tuberculosis, with no reactivation during TNFα antagonist therapy." (PMID 19886992, 2009). "TNFα levels were raised in pulmonary as compared with both extra-pulmonary tuberculosis and controls in response to LPS but not BCG stimulation." (PMID 16001981, 2005). "Newly diagnosed smear positive pulmonary tuberculosis/immunological and autophagy biomarkers (T cell, monocyte and dendritic cell functions ESAT-6/CFP-10, Culture filtrate Protein, estimation of C reactive protein, tumor necrosis factor-alpha and other cytokines)." (PMID 32410999, 2020). "Similarly, in the absence of standard anti-TB therapy, administration of anti-TNF-α antibodies exacerbates disease severity in a mouse model of pulmonary TB." (PMID 29094039, 2017). "Other studies demonstrated that TNF-α level in BALF in smear-negative active pulmonary TB patients were 4.4-fold higher than that in the controls, and higher TNF-α mRNA expression levels in the lungs of mice with latent tuberculosis infection (LTBI) compared to the controls." (PMID 22889060, 2012). "Screening for LTBI prior to anti-TNFα initiation was negative in 20 (67%) of 30 patients; among the other 10 patients, 6 (21%) were treated for LTBI, 1 (3%) for pulmonary TB, and 3 (8%) had no screening." (PMID 38957691, 2024). "There were significant immune responses and increases in IFN-γ, TNF-α, and VEGF in the lung parenchyma of TPE patients without pulmonary tuberculosis." (PMID 22889060, 2012). "The concentrations of interferon-γ (IFN-γ), tumor necrosis factor-α (TNF-α), vascular endothelial growth factor (VEGF), and the CD4+/CD8+ ratio of T-lymphocytes were significantly higher in TPE patients without pulmonary tuberculosis than in the controls." (PMID 22889060, 2012).
pulmonary TB (continued). "In the present study, we found that BALF from TPE patients without pulmonary tuberculosis contained increased levels of IFN-γ, TNF-α, and VEGF." (PMID 22889060, 2012). "The following cytokine ratios were found to be different between non-TB diseases and pulmonary TB: PPD induced IFN-γ/IL-2 (p<0.001) and ESAT-6 induced TNF-α/IFN-γ (p = 0.048)." (PMID 22523581, 2012). "We demonstrated significantly high levels of TNF-α, IFN-γ, and VEGF and an increased CD4+/CD8+ ratio of T lymphocytes in BALF from TPE patients without active pulmonary tuberculosis." (PMID 22889060, 2012). "We measured the TNF-α level in BALF of newly diagnosed, untreated TPE patients without pulmonary tuberculosis." (PMID 22889060, 2012). "In our study, we have observed elevated levels of TNF-α to Ag85A, Ag85B, and ESAT-6 in patients with pulmonary tuberculosis or undergoing treatment but not in extra-pulmonary TB patients." (PMID 21253450, 2011).